SNORD86 (small nucleolar RNA, C/D box 86)
Synonyms: U86
Gene: Small nucleolar RNA gene on chromosome 20 (2,656,097 to 2,656,182, forward strand). Ensembl gene ENSG00000212498.
Gene Ontology:
Biological process: RNA processing
Cellular component: nucleolus
Homologues: Orthologues: chimpanzee SNORD86 (100% identical), macaque SNORD86 (100% identical), pig SNORD86 (97% identical), rabbit SNORD86 (97% identical), mouse Gm23187 (94% identical), rat Snord86 (91% identical), guinea pig SNORD86 (88% identical).